IL27 (interleukin 27)
Diseases named in the same sentence as IL27 in open-access papers (continued):
Sharing a sentence is not in itself a finding about the gene and the disease.
asthma (29 papers, 2008 to 2025). "IL-27 is a heterodimeric cytokine expressed by macrophages and monocytes that has been implicated in the etiopathogenesis of chronic corticosteroid-induced asthma." (PMID 40136649, 2025). "A recent study showed that the rs153109 promoter polymorphism of IL-27 probably influences gene transcription by altering its binding to transcription factors and that the AA genotype or A allele confers susceptibility to asthma." (PMID 30268141, 2018). "In humans, single nucleotide polymorphisms in IL-27p28 are associated with asthma susceptibility, increased IgE, and eosinophilia, while IL-27 expression may play a role in severe asthma." (PMID 29118754, 2017). "The associations between polymorphisms of IL-27 gene, as well as serum/plasma levels of IL-27 and various human disorders including asthma, inflammatory bowel diseases, chronic obstructive pulmonary disease (COPD), colorectal cancer, esophageal cancer, and glioma have been studied." (PMID 26014498, 2015). "Interestingly, human studies, such as on inflammatory bowel diseases and asthma, have described that all the single nucleotide polymorphisms (SNPs) relating with IL-27 have been associated with IL-27p28." (PMID 25633106, 2015). "In contrast to Tregs, IL-27 appears to act differently in asthma suppression; when IL 27 was administrated therapeutically, IL 27 did not ameliorate airway inflammation, airway hyperresponsiveness, and airway remolding." (PMID 39066375, 2024). "Because IL-27 targets Tregs in asthma models and reduces respiratory allergy symptoms, the asthma-relieving effects of Δpep27 appear to be due to the suppression of inflammation by IL-27-induced Tregs." (PMID 39066375, 2024). "In asthma models, IL-27 is an anti-inflammatory cytokine that belongs to the IL-12 family and is primarily expressed on dendritic cells, macrophages, and monocytes." (PMID 39066375, 2024). "Recent studies have confirmed that innate lymphoid cells (ILC) are also an important source of these factors Current studies have shown that IL-27, as an immunomodulatory factor, inhibits airway inflammation and airway hyperresponsiveness in asthma." (PMID 38117410, 2024). "At present, animal experiments have confirmed the role of IL-27 in inhibiting the pathogenesis of asthma, but different clinical studies have reported different levels of IL-27 expression in asthma patients." (PMID 38117410, 2024). "The administration of IL-27 via intranasal route has been shown to mitigate Th2-mediated allergic lung inflammation and restructuring in murine asthma models through the restoration of both STAT1 and STAT3 signaling pathways." (PMID 39062111, 2024). "The objective of this study was to clarify the impact and mechanism of regulation of the IFN-γ/DC/IL-27/Th9 axis on AA, providing novel insights for the effective targeted treatment of asthma." (PMID 36304255, 2022). "This study aimed to clarify the regulatory effect and mechanism of the IFN-γ/DCs/IL-27/Th9 axis on AA and provide novel insights for effective targeted treatment of asthma." (PMID 36304255, 2022). "In spite of an existing body of literature supporting a protective role of IL-27 against Th2 and asthma, a recent report suggested divergent effects in human asthma." (PMID 28255204, 2017). "There is some evidence that IL-27 dysfunction contributes to asthma pathophysiology, though little attention has been directed to the role of IL-27 in HRV infections." (PMID 29118754, 2017). "Together, these results demonstrate that differentiated Th2 cells in the complex asthma environment also resist IL-27-mediated inhibition in vivo." (PMID 27687913, 2016). "More importantly, preventative administration of IL-27 caused significant protection from methacholine-induced AHR, a hallmark of asthma." (PMID 27687913, 2016). "Our pilot study indicates a promising role for IL-27, a pleiotropic cytokine,in alleviating the pathogenesis of mouse asthma with the proper administration route and timing." (PMID 27687913, 2016).
asthma (continued). "In vivo study, the effect of IL-27 was examined using two types of intra-nasal (i.n.)administration: low-dose-multiple-times prevention or high-dose-limited-times treatment in murine asthma models." (PMID 27687913, 2016). "This research sheds light on cytokine treatment, especially that involving IL-27, which has the potential to be used as an intervention in asthma prevention and management in the future." (PMID 27687913, 2016). "IL-27 is a monocyte- and macrophage-derived innate cytokine that is probably involved in the pathogenesis of severe, corticosteroid-resistant asthma." (PMID 23853765, 2013). "Furthermore, IL27 rs153109 (-964A/G) has been related to many diseases such as inflammatory bowel disease and asthma." (PMID 40057761, 2025). "IL-27 may be a promising candidate for novel treatment approaches designed to improve the management of chronic, corticosteroid-resistant asthma." (PMID 40136649, 2025). "The inhibitory effect of IL-27 on airway inflammation and airway hyperresponsiveness in asthma may be the combined effect of different types of Th cells regulated by IL-27." (PMID 38117410, 2024). "Prophylactic injection of IL-27 reduced the concentration of Th2 cytokines and increased the number of type 1 regulatory T cells in mice, thereby reducing the lung inflammatory environment and improving asthma." (PMID 39175819, 2024). "So, in the asthma disease environment, whether IL-27 has a similar ‘autocrine’ regulatory effect on dendritic cells is rarely reported in the relevant literature." (PMID 38117410, 2024). "In recent years, reports on IL-27 involved in the regulation of airway inflammation and airway hyperresponsiveness in asthma have been increasing, but different studies have controversially discussed the role and mechanism of IL-27 in the pathogenesis of asthma." (PMID 38117410, 2024). "Research on the role of IL-27 in asthma has indicated that IL-27 may increase the expression of T-bet mRNA by promoting IFN-γ expression, inhibiting IL-4 synthesis, and enhancing the Th1 response." (PMID 36304255, 2022). "We speculated that IFN-γ inhibits Th9 differentiation by regulating the secretion of interleukin (IL)-27 from dendritic cells (DCs), thereby suppressing airway inflammation in asthma." (PMID 36304255, 2022). "The previous studies have found that the level of IL-27 is increased in patients with tuberculosis, asthma, influenza, acute lung injury, lung cancer, chronic obstructive pulmonary disease (COPD), acute lung injury (ALI) and acute respiratory distress syndrome (ARDS) 11-15." (PMID 34975300, 2022). "Herein, we speculated that IFN-γ can inhibit Th9 differentiation by regulating the secretion of IL-27 by DCs, thereby suppressing airway inflammation in asthma." (PMID 36304255, 2022). "Similarly, the expression, distribution, and upstream regulation of IL-27 in asthma and regulation of the Th9 response, which plays a vital role in the pathogenesis of asthma, remain unreported." (PMID 36304255, 2022). "TLR7/8 agonist R848 suppresses experimental asthma by increasing IL-27 level." (PMID 34234781, 2021). "In mouse models of OVA-induced asthma, the intranasal IL-27 administration significantly improves the clinical symptoms of the disease, decreases the local eosinophilia in the nasal mucosa, modulates the cytokine production by Th1, Th2, and Treg cells, and decrease the serum levels of specific IgE." (PMID 32849534, 2020). "Interestingly, although IL‐27 production was increased in the IfitmF–/– mice compared to WT in our asthma experiments, levels of Il4, IL‐5, IL‐13, IL‐6, IL‐10, IL17, and TNF‐α were all decreased." (PMID 30365177, 2019). "Intranasal treatment with IL-27 inhibited airway inflammation in an asthma model." (PMID 28255204, 2017). "In addition, coexpression of IL-27 with CCL26 mRNA, which is prototypical of a Th2/IL-13 signature, was associated with severe asthma." (PMID 28255204, 2017).
asthma (continued). "We further administrated IL-27 intro-nasal to see whether IL-27 has the capacity to alleviate airway inflammation in asthma mice model." (PMID 27687913, 2016). "In the present study, we proved that IL-27 did not inhibit the already differentiated Th2 cells in both mouse and human systems in vitro This might result in the inability of therapeutic i.n. administration of IL-27 to improve the pathological asthma symptoms." (PMID 27687913, 2016). "We use human/mouse CD4+ T cells to see whether IL-27 could inhibit IL-4 production in vitro and then observe whether IL-27 administration could alleviate allergic airway inflammation in vivo by mice asthma model." (PMID 27687913, 2016). "Having demonstrated that differentiated Th2 cells resist IL-27-mediated inhibition in vitro, we wanted to further investigate whether the inhibition effect works in vivo in a mouse asthma model." (PMID 27687913, 2016). "In addition, IL-27 is a member of the IL-6/IL-12 family of cytokines, and rare variants in IL12RB1 have been previously implicated in asthma, suggesting that this family of cytokines and receptors should be the target of additional studies." (PMID 25116239, 2014). "Moreover, IL-17 and IL-23, as well as the innate cytokines TSLP, IL-25, IL-33, and IL-27, are additional interesting targets for future asthma therapies." (PMID 23853765, 2013). "This study aimed to examine whether IL-27 regulated the CD39/ATP axis of dendritic cells in asthma." (PMID 38117410, 2024). "Prophylactically, administration of IL-27 decreased the concentration of Th2 cytokines and increased the number of type 1 regulatory T (Tr1) cells in the lungs, suggesting that IL-27 may prevent asthma." (PMID 39066375, 2024). "Furthermore, we investigated the effects of preventive and therapeutic IL-27 administration on the allergic airway inflammation in ovalbumin (OVA)-induced asthma mouse models and studied whether the effect is related to the STAT1 and GADD45γ/p38 MAPK pathways." (PMID 27687913, 2016). "In the prevention group, IL-27 was administered before OVA sensitization when the CD4+ T cells were largely naïve and could be promoted to differentiate into Th1 cells by IL-27, supporting an environment of Th1 cells before the asthma challenge could alleviate the onset of an asthma attack." (PMID 27687913, 2016). "Moreover, for the methacholine-induced AHR, a hallmark of asthma, the IL-27 treatment also offered no significant protection." (PMID 27687913, 2016). "Manipulating IL-27 may provide a novel therapeutic strategy for the treatment of asthma." (PMID 25331546, 2015). "Therefore, IL-27 may represent a potential target for new therapeutic strategies aimed to provide a better control of severe, steroid-refractory asthma." (PMID 23853765, 2013). "The role of IL-27 modulation in human asthma is still unknown." (PMID 18315837, 2008). "Also, anti-inflammatory cytokines such as IL-10, IL-12, IL-18, IL-21, IL-23, IL-27 and interferons may have a therapeutic potential in asthma." (PMID 18315837, 2008). "The effects of IL-27 on mast cells are not extensively studied in ARDS but have typically been explored in the context of asthma or allergy." (PMID 41024268, 2025). "Moreover, there is growing evidence for the role of IL-27 as a contributor to a range of pulmonary diseases including ARDS, COPD, tuberculosis, asthma, acute lung injury and influenza 11-13." (PMID 34975300, 2022). "Further, limited high-dose administration of exogenous IL-27 in the challenge stage of asthma did not effectively suppress Th2-mediated allergic asthma." (PMID 27687913, 2016). "It is possible that the differentiated Th2 cells mediated the lack of improvement of airway inflammation in the asthma mouse model following therapeutic intra-nasal administration of IL-27." (PMID 27687913, 2016). "Therapeutic administration of IL-27 in the challenge stage of asthma did not effectively suppresses Th2-mediated allergic asthma." (PMID 27687913, 2016).
asthma (continued). "The mechanism of IL-27 in asthma has not been fully elucidated." (PMID 38117410, 2024). "In contrast, the low-dose preventative administration of IL-27 with multiple administrations could either reverse the impairment of the STAT1 pathway or strengthen the GADD45γ/p38 MAPK pathway and improve the pathologic symptoms of asthma." (PMID 27687913, 2016). "In the beginning, we administered IL-27 for 7 days after OVA sensitization but before the OVA challenge and obtained no significant improvement in asthma symptoms." (PMID 27687913, 2016). "To test this hypothesis, we administered IL-27 to OVA-immunized mice at two concentrations (25 and 50 ng/mouse) twice a day for 7 days before the OVA challenge (after the second OVA sensitization), and there seemed to be no obvious improvement in the mouse asthma model." (PMID 27687913, 2016).
influenza (29 papers, 2014 to 2025). An acute viral infection of the respiratory tract, occurring in isolated cases, in epidemics, or in pandemics; it is caused by serologically different strains of viruses (influenzaviruses) designated A, B, and C, has a 3-day incubation period, and usually lasts for 3 to 10 days. "Studies with different models including viral (influenza) ones show that IL-27 is a critical negative regulator of the pathology associated with these models (such as parasitic, bacterial, viral, autoimmune and others)." (PMID 34996392, 2022). "A previous study has reported that during S. aureus secondary co-infection post influenza infection, IL-27 produced in response to the virus increased susceptibility to S. aureus pneumonia in an IL-10 dependent manner." (PMID 35776778, 2022). "Analyses of transcripts encoding Il12p35, Il12p40, Il23p19, and Il27p28 indicated that IL-27 was produced during the early phase of influenza infection between DPIs 4–7 both in the alveolar space and lung tissues." (PMID 30899058, 2019). "A more recent study in mice demonstrated that influenza-induced IL-27 led to a predisposition to secondary pneumococcal pneumonia due to suppression of IL-17A." (PMID 30192848, 2018). "In conclusion, our study supports that IL-27 signaling regulates enhanced susceptibility to S. aureus pneumonia following influenza infection, potentially through both the induction of IL-10 and suppression of IL-17." (PMID 25651926, 2015). "In vivo, we further found that IFNAR-deficient mice after influenza infection had much less IL-27 protein in the lungs compared with WT mice." (PMID 24408967, 2014). "Indeed, experiments in murine influenza infection demonstrated that IL-27 restricts virus-induced pathology associated with exuberant neutrophil, TH1 and TH17 responses." (PMID 27926930, 2016). "IL-27 was necessary to protect against weight loss during influenza infection." (PMID 25651926, 2015). "Interestingly, IL-27 also inhibits Type 17 immunity, and so could have synergistically enhanced susceptibility to S. aureus infection following influenza infection via inhibition of Th17 immunity." (PMID 34079555, 2021). "Since influenza infection was associated with profoundly elevated IL-27 production in the lungs of mice, we investigated whether the induction of IL-27 was responsible for altering innate immunity in such a way that secondary pneumococcal replication was enhanced." (PMID 24408967, 2014). "Limited data is available on dynamics of IL-27 in the setting of human influenza infection, IL-27 serum levels were reported to be increased in individuals infected with seasonal IAV (H3N2) and H1N1." (PMID 38966644, 2024). "Mechanistically, influenza infection models have demonstrated that IL-27 augments IL-10 production by CD8+ T cells synergistically with IL-2 by promoting and sustaining expression of IRF4 and B-lymphocyte maturation protein-1 (Blimp-1)." (PMID 35634328, 2022). "IL-27 also has potent antiviral effects against influenza, hepatitis B and C viruses, human immunodeficiency virus and others, by stimulating IFNγ production by CD8+ T cells and modulating innate responses." (PMID 36148243, 2022). "IL-27-/- mice displayed significantly decreased IL-10 production compared to WT mice upon infection with influenza, which led to enhanced bacterial clearance alongside decreased IL-10 production and higher Th-17 associated responses." (PMID 35776778, 2022). "Regarding timing, this was illustrated recently in an influenza model, where IL-27 plays an important role in limiting destructive inflammation (protective), particularly in the resolving (late) phase of infection." (PMID 35735491, 2022). "IL-27 inhibition in a murine model of secondary Staphylococcus aureus pneumonia following influenza infection also improved bacterial clearance." (PMID 34079555, 2021).